ENSG00000310562 (novel protein similar to mitochondrial fission factor MFF)
Gene: Protein-coding gene on chromosome X (45,730,995 to 45,732,455, forward strand). Ensembl gene ENSG00000310562.
Homologues: Orthologues: pig MFF (78% identical), tropical clawed frog mff (58% identical), zebrafish mffb (49% identical), zebrafish mffa (39% identical), Drosophila melanogaster Tango11 (23% identical), Caenorhabditis elegans mff-2 (16% identical). Paralogues in human: MFF (78% identical).